LRRC8C (leucine rich repeat containing 8 VRAC subunit C)
Description:
Non-essential component of the volume-regulated anion channel (VRAC, also named VSOAC channel), an anion channel required to maintain a constant cell volume in response to extracellular or intracellular osmotic changes. The VRAC channel conducts iodide better than chloride and can also conduct organic osmolytes like taurine. Plays a redundant role in the efflux of amino acids, such as aspartate and glutamate, in response to osmotic stress. The VRAC channel also mediates transport of immunoreactive cyclic dinucleotide GMP-AMP (2'-3'-cGAMP), an immune messenger produced in response to DNA virus in the cytosol. Channel activity requires LRRC8A plus at least one other family member (LRRC8B, LRRC8C, LRRC8D or LRRC8E); channel characteristics depend on the precise subunit composition.
Synonyms: AD158; FAD158; TIMES
Tractability: Antibody: UniProt places it where antibodies can reach, with high confidence; its Gene Ontology location is reachable by antibodies, with high confidence; UniProt predicts a signal peptide or a membrane-spanning region. PROTAC: ubiquitination databases record sites on it; its protein half-life has been measured.
Gene: Protein-coding gene on chromosome 1 (89,632,707 to 89,769,903, forward strand). Ensembl gene ENSG00000171488.
Subcellular location: Cell membrane; Endoplasmic reticulum membrane
Subcellular location (Human Protein Atlas): Golgi apparatus
Pathways (Reactome):
Transport of small molecules: Miscellaneous transport and binding events
Gene Ontology:
Molecular function: protein binding; volume-sensitive anion channel activity
Biological process: cyclic-GMP-AMP transmembrane import across plasma membrane; monoatomic anion transmembrane transport; aspartate transmembrane transport; protein hexamerization; cellular response to osmotic stress; taurine transmembrane transport
Cellular component: cytoplasm; membrane; plasma membrane; monoatomic ion channel complex; endoplasmic reticulum; endoplasmic reticulum membrane
Genetic constraint (gnomAD): Loss-of-function variants: 20 observed, 56.54 expected, observed/expected ratio (o/e) 0.35, 90% interval 0.25 to 0.51. The upper end of that interval is the gene's LOEUF score, 0.51, which puts it in group 2 of 6, group 1 being the genes least tolerant of losing a copy. Missense variants: 655 observed, 1,000.8 expected, observed/expected ratio (o/e) 0.65, 90% interval 0.61 to 0.7. Synonymous variants: 376 observed, 382.24 expected, observed/expected ratio (o/e) 0.98, 90% interval 0.9 to 1.07.
Homologues: Orthologues: chimpanzee LRRC8C (99% identical), macaque LRRC8C (99% identical), dog LRRC8C (99% identical), guinea pig LRRC8C (99% identical), rabbit LRRC8C (98% identical), rat Lrrc8c (98% identical), mouse Lrrc8c (97% identical), pig LRRC8C (97% identical), tropical clawed frog lrrc8c (83% identical), zebrafish lrrc8c (77% identical), tropical clawed frog XB964897 (64% identical). Paralogues in human: LRRC8E (61% identical), LRRC8A (58% identical), LRRC8D (52% identical), LRRC8B (51% identical), PHLPP1 (16% identical), SCRIB (16% identical), PHLPP2 (15% identical), LRRC1 (14% identical), ERBIN (14% identical), LRRC40 (14% identical), LRRC7 (13% identical), LRRD1 (13% identical), and 19 more.
Diseases named in the same sentence as LRRC8C in open-access papers:
LRRC8C is named in the same sentence as 16 diseases in open-access papers, as found by Europe PMC text mining. Sharing a sentence is not in itself a finding about the gene and the disease. The quoted sentences say what the papers report.
immune deficiencies (1 paper, 2025). "Genetic variants in LRRC8A and other LRRC8 subunits, such as LRRC8C have been identified in human populations and are primarily associated with immune deficiencies and developmental disorders." (PMID 40299635, 2025).
liver cancer (1 paper, 2024). An epithelial or non-epithelial malignant neoplasm that arises from the liver. "Together, these data indicate that LRRC8C channels mediate cGAMP transmission from liver cancer cells to vascular endothelial cells, thereby activating endothelial STING pathway." (PMID 38177099, 2024).
lung adenocarcinoma (1 paper, 2024). A carcinoma that arises from the lung and is characterized by the presence of malignant glandular epithelial cells. "Paired t-tests suggested that compared with normal lung tissue, LRRC8C mRNA was significantly down-regulated in combined lung squamous cell carcinoma (LUSC) + lung adenocarcinoma (LUAD), LUSC, and LUAD (all P < 0.0001)." (PMID 39416786, 2024).
tumor (6 papers, 2008 to 2024). "Tumor LRRC8C expression negatively correlated with vascular invasion when cGAS was highly expressed, whereas no obvious correlation was shown in low cGAS expression group." (PMID 38177099, 2024). "Of these, angiopoietin 2 (ANGPT2), protocadherin 12 (PCDH12) and leucine rich repeat containing 8 family member C (LRRC8C) had expression profiles completely restricted to tumour or foetal tissues." (PMID 18394197, 2008). "Moreover, we performed immunofluorescence analysis in the tumor mass of ADEVs-treated mice; we observed a significant decrease in the LRRC8C protein expression with respect to vehicle-treated mice." (PMID 36428520, 2022). "cGAMP can be also released by tumor cells and activate neighboring cells following entry via bidirectional transporters like LRRC8A and LRRC8C/E heteromeric channels." (PMID 36280676, 2022). "Furthermore, HCC patients with high tumor TET2, p-STAT5A, cGAS, LRRC8C, and endothelial STING expression had better clinical outcome." (PMID 38177099, 2024).
cancer (3 papers, 2022 to 2024). A tumor composed of atypical neoplastic, often pleomorphic cells that invade other tissues. "LRRC8C is a component of the volume-regulated anion channel (VRAC) that has been recently linked to multidrug resistance in cancer in compounds such as cisplatin." (PMID 35639775, 2022). "LRRC8C is a potential cancer gene-related gene, and most of the current studies focused on the immune system." (PMID 38025711, 2023). "Since LRRC8 channels have been proved to be a bidirectional cGAMP transporter, we next determined whether cGAMP secreted by cancer cells enters endothelial cells also through LRRC8C." (PMID 38177099, 2024).
LRRC8C also shares sentences with these, for which no sentence is quoted: Ataxia (1 paper); ataxia telangiectasia (1); breast carcinoma (1); Intellectual disability (1); lung squamous cell carcinoma (1); mastitis (1); Metaphyseal dysplasia (1); microcephaly (1); neurodegenerative disease (1); Obesity (1); Telangiectasia (1).